IL6 (interleukin 6)
Diseases named in the same sentence as IL6 in open-access papers (continued):
Sharing a sentence is not in itself a finding about the gene and the disease.
cancer (continued). "This alteration enhances elevated levels of cytokines such as IL-6 and TNF-α to drive cancer progression." (PMID 39156288, 2024). "To address any potential bias arising from the effects of sgp130Fc in a single cell type, particularly a cancer cell line such as A549, we evaluated the IC50 values of sgp130Fc for IL6 cis-signalling in primary human hepatocytes and HSCs." (PMID 38338642, 2024). "We first measured the levels of IL-6 and GDF-15 in the blood at different timepoints of cancer progression in this model." (PMID 38824130, 2024). "In this context, Cheng Wei and collaborators described a positive feedback loop between cancer cells and TAMs involving the IL6/STAT3 pathway, with a critical role in cancer progression and metastasis." (PMID 38391950, 2024). "Polarization of neutrophils to the N2 type exhibits a longer lifespan and releases IL-6 and NET to promote cancer development." (PMID 38165570, 2024). "Many studies have demonstrated that IL-6-specific functions in CAFs involve the IL-6/CXCR7 axis and the IL-6/Jak1/STAT3 axis, which play roles in the immune response, EMT and cancer cell migration." (PMID 39075612, 2024). "The other direction of IL-6 and EMT interaction, i.e., if, and how, the acquisition of mesenchymal phenotype by cancer cells promotes the development of inflammatory and immunosuppressive characteristics of TME, is also investigated." (PMID 39201656, 2024). "miRNA modulates epigenetically and disrupts IL6, IL6R, and its pathway, and their role has been observed in various cancers." (PMID 39766086, 2024). "CAFs derived from ASCs secrete factors like TGF-β, IL-6, and CXCL12 that can trigger the EMT in cancer cells, enhancing their migratory and invasive potential." (PMID 39519109, 2024). "Furthermore, owing to increased metabolic activity during SKM contractile activity, SKM temperature increases; this higher temperature may augment recruitment of natural killer cells and thus help to prevent cancer development or metastasis, potentially in an interleukin (IL)-6-dependent manner." (PMID 38928185, 2024). "The course of the disease is determined by proinflammatory cytokines such as interleukin-6 (IL-6) and C-reactive protein (CRP), as well as the existence of co-morbidities such as cardiovascular, respiratory, metabolic, and cancer." (PMID 39280382, 2024). "The upregulation of PD-L1, TGF-β, IL-6, and TNF-α observed in c-Mel represents further evidence on the immunosuppressive roles of TAFs and TAMs on cancer cells." (PMID 37612575, 2024). "Cancer controls (B) receiving only AOM showed statistically the highest number of pro-inflammatory cytokines (TNF-α and IL-6) and lowest anti-inflammatory cytokines (IL-10) in their tissue homogenates." (PMID 38191592, 2024). "The activated IL-6/STAT3 pathway can inhibit caspase-dependent apoptosis, promoting proliferation and metastasis of cancer cells." (PMID 38673967, 2024). "IL-6 is synthesized by various cell types, including AFs, CAFs, and cancer cells in the TME, promoting cancer spread and resistance to chemotherapy." (PMID 38519574, 2024). "Activation of STAT3 in cancer cells leads to proliferation and suppression of apoptosis and we can observe that in BC where STAT3 is activated by elevated levels of IL-6 and IL-10." (PMID 38892394, 2024). "ADSCs secrete immunosuppressive cytokines such as IL-6, IL-8, and TGF-β1, which inhibit local immune reactions against cancer cells, thus enabling cancer to progress toward more aggressive phenotypes." (PMID 39590296, 2024). "WAT releases inflammatory molecules, such as IL6, TNF, and CCL2, which can contribute to cancer progression by promoting inflammation." (PMID 39011399, 2024).
cancer (continued). "There is a potential role for the use of biomarkers in the diagnosis of cancer cachexia—human CC patients have been demonstrated to have elevated C-reactive protein (CRP), fibrinogen, IL1, IL6 and TNF-a." (PMID 38674936, 2024). "The accumulation of IL6 also stimulates Metalloproteinase-9 (MMP9) production in OC, promoting cancer cell invasion and degradation of the extracellular basement membrane." (PMID 39766086, 2024). "Correlation analysis with immunohistochemistry findings showed that the degrees of CD4 + and CD163 + cell infiltration and IL-6 and MMP-11 expression were correlated with cancer imaging features on PET/CT." (PMID 38627864, 2024). "Furthermore, elevated IL-6 levels can have a detrimental impact on the immune response, thereby creating a favorable microenvironment for the development of infectious processes, a situation that poses significant risks and is frequently encountered in cancer patients." (PMID 38337668, 2024). "To explore similar mechanisms in other cancers, we conducted a correlation analysis of CD59 with macrophage, IL10, IL10RB, IL6, and IL6R on KIRC, CESC, GBM, HNSC, and STAD." (PMID 39518137, 2024). "In a feedback loop, the polarized macrophages secreted IL-6, which further activated STAT3 signaling in UBC cells, thus maintaining cancer stemness." (PMID 39479456, 2024). "This indicates that there is an enhanced amount of the IL-6-inducing neo-structure present in cancer patient sera and that such neo-structures are produced selectively in PBMC cultures from cancer patients, probably due to a unique set-up of proteases." (PMID 39518029, 2024). "In the present study, we extend these observations by demonstrating that Tu-Gr1+CD11b+–derived IL-6 and OSM twist cancer cell plasticity by promoting a rapid but reversible conversion of SCA1– cells into more metastatic SCA1+ cells." (PMID 38236642, 2024). "BC cell derived GLUT3 triggers lactate-mediated CXCL8 secretion by cancer cells leading to TAM M1 polarization and expression of IL-1β, TNF-α and IL-6." (PMID 39044824, 2024). "Antibodies targeting specific components of the SASP like IL-6 and IL-8 have shown promise in preclinical studies, indicating the potential for targeted SASP modulation in cancer therapy." (PMID 38913050, 2024). "TAMs are an important source of IL-6, which regulates the expression of m6A regulators and activates the JAK2/p-STAT3 pathway in cancer cells." (PMID 38872221, 2024). "Upon activation, IL-6 also stimulates the JAK/STAT, PI3K, and MAPK pathways, which mediate inflammation and cancer development." (PMID 39027148, 2024). "NF-κB is well understood to be involved in many molecular processes, such as IL-6, TNF-α, and TLR4, in cancer." (PMID 38997762, 2024). "Meanwhile, RT has been shown to prevent cancer-induced myofiber atrophy, reduce inflammation by reducing the expression of TNF-α and IL-6, and mitigate oxidative damage by inducing cytochrome oxidase." (PMID 38791998, 2024). "We investigated the role of the IL-6-induced GP130/JAK2/STAT3 pathway in the proliferation, migration, and EMT of KSCs, as these properties are known to promote cell metastasis in cancer." (PMID 38519574, 2024). "In the cancer cohort (N = 65), low circulating HGF (P = 0.023, P = 0.029), low IL-6 (P = 0.002, P < 0.001), and high CCR (P = 0.031, P = 0.008) were associated with significantly improved progression-free survival (PFS) and overall survival (OS)." (PMID 38776028, 2024). "These herbs exhibit effectiveness against inflammatory cytokines, such as IL-6, IL-8, and TNF-alpha; inhibit cancer growth; regulate VEGF expression; and modulate the immune system." (PMID 38543097, 2024).
cancer (continued). "For instance, antibodies against specific SASP components like IL-6 and IL-8 have shown promise in preclinical studies, highlighting the potential for targeted SASP modulation in cancer therapy." (PMID 38913050, 2024). "Then, the p50/p65 complex transfers into the nucleus to enhance levels of IL-6, IL-8, Bcl-2, Bcl-xL, MMPs, and CCND1 in increasing cancer progression and reducing apoptosis." (PMID 39014491, 2024). "Another study indicated that after treatment with the nanoformulated LPO and LF on chitosan NPs, there was a considerable suppressed various pro-inflammatory markers, including TNF-α, IL-6, VEGF, and NF-κB in the treated breast MCF-7 and MDA cancer cells." (PMID 39438495, 2024). "In cancer, STAT3 is involved in a complex network of signaling pathways (including NF-κB and IL-6) and alternative splicing events, resulting in the production of two isoforms: STAT3α and STAT3β." (PMID 39309860, 2024). "Loss of Lect2 fosters the accumulation/activation of M-MDSC, leading to the presence of M2-like TAMs and pro-tumorigenic cytokines (IL-4, IL-6, IL-10, and TGF-β) that can impair the activity of T cells in the fight against cancer." (PMID 38177412, 2024). "For instance, cancer cells can induce the generation of iCAFs by releasing IL1β, which activates the LIF/JAK/STAT3 axis and subsequently triggers the expression of IL6." (PMID 38453816, 2024). "Two different cancer markers, including tumor necrosis factor alpha (TNF-α, 17.3 kDa) and interleukin-6 (IL-6, 20.9 kDa), were used in this targeting experiment." (PMID 38161210, 2024). "Plasma levels of C‐reactive protein (CRP), interleukin‐6 (IL‐6) and YKL‐40 reflect inflammation, and are elevated in patients with cancer." (PMID 36440611, 2023). "Of the shared measures in both sexes, IL-6 and IL-10 increased the most as the disease progressed (DFSO) or worsened (clinical score) and in patients with BMI > 30 and those with prior cancer treatment." (PMID 37998327, 2023). "According to reviews, increased neutrophil and monocyte counts, along with elevated levels of various inflammatory markers such as IL-6, IL-1β, and CRP, have been found to be correlated with fatigue in cancer survivors." (PMID 37507961, 2023). "Secreted factors such as MIF, IL‐6, CD40L, FST, SDF‐1α and IL‐8 were expressed at higher levels in conditioned medium from PC3 cancer cells." (PMID 36608258, 2023). "The IL6/JAK/STAT3 signaling pathway is frequently activated in various human cancers driving cell proliferation, migration/invasion, and cancer metastatic dissemination." (PMID 37173331, 2023). "IL-6, IL-17, TNF-α, TLR-2, and TLR-4 were significantly more highly expressed in the cancer tissues (p < 0.05)." (PMID 38075864, 2023). "Certain signaling pathways were increased in cancer patient PBMCs (IL-10-induced p-STAT3 in helper T, Treg, and cytotoxic T cells) while others were decreased (IL-6 induced p-STAT1 in helper T, Treg, and cytotoxic T cells) compared to healthy control PBMCs." (PMID 37741983, 2023). "MSCs participate in the regulation of BCSCs by secreting interleukin-6 (IL-6) and cytokine CXCL7, thereby promoting BCSC self-renewal and cancer cell proliferation." (PMID 38001753, 2023). "Meanwhile, the interleukin 6 (IL6), CXC chemokine Ligand-5 (CXCL5), and CXC chemokine Ligand-10 (CXCL10) expressions were inhibited, and the cancer-promoting effect was reversed by COL12A1 knockdown." (PMID 36900272, 2023). "NE can also stimulate the production of IL-6 and activate macrophages in TME, which can promote cancer migration and nerve invasion by releasing GDNF." (PMID 36900158, 2023). "Interleukin 6 sends signals to the cell nucleus via a signal transducer to Transcription Activator 3 (STAT3), an oncoprotein activated in many cancerous tumors." (PMID 36981858, 2023). "STAT3 is known to contribute to ALDHhigh cell homeostasis in various cancer settings and STAT3 activation is a main signaling event after IL-6 stimulation of the cells." (PMID 37460938, 2023).
cancer (continued). "Among patients diagnosed with cancer within 3 months, 44% had elevated CRP, 60% had elevated IL‐6 and 45% had elevated YKL‐40." (PMID 36440611, 2023). "Adiponectin, leptin, IL-6, TNF-α, YKL-40 (chitinase-3-like-protein-1), osteopontin, and plasminogen activator inhibitor-1 (PAI-1) are all produced by adipocytes and stimulate cancer growth, progression, and metastasis." (PMID 37229273, 2023). "Activated fibroblasts are reported to secrete various growth factors, cytokines such as SDF-1, IL-6, CXCL14, CCL5 and CCL7 and proteases such as MMP-2, MMP-9 and uPA to promote EMT in cancer." (PMID 37065872, 2023). "Presently, IL-6 is regarded as a major regulator of MDSC activity and a possible target for cancer immunotherapy." (PMID 37108179, 2023). "Although little is known about the precise mechanism by which CAFs control NK cell activity, cytokines secreted by CAFs and cancer cells, such as TGF-β, prostaglandin E2, indoleamine-2,3-dioxygenase, and IL-6, were reported to regulate NK cell activity." (PMID 37759302, 2023). "Related studies in advanced cancer showed that Infliximab was well tolerated with few toxic effects, and it decreased inflammatory factors including CCL2, IL-6 and serum CRP." (PMID 38201482, 2023). "The gp130 family members, IL-11, IL-6, OSM, and LIF (upregulated in the LM) potentially impact skeletal muscle wasting by inducing the STAT3 signaling pathway in the preclinical model of cancer cachexia." (PMID 36774484, 2023). "For instance, factors such as IL-6 and IL-1 (both of which induce JAK/STAT signalling) are secreted by cancer cells to promote CAF activation." (PMID 37190281, 2023). "mRNA levels for the cancer progression-related genes HPV16-E6, HPV16-E7, IL6, and MAP7 were significantly downregulated in SiHa cells treated with CLD compared to control cells, while LTF was upregulated." (PMID 37344615, 2023). "IL-6, one of the major cytokines in the TME, promotes tumorigenesis by regulating the hallmarks of cancer and multiple signaling pathways." (PMID 36797769, 2023). "Effective inhibition of IL-6-induced signaling and transcription activator 3 (STAT3) phosphorylation can significantly downregulate the invasive ability of cancer cells." (PMID 37990309, 2023). "Proinflammatory cytokines, including IL-1, IL-6, and TNF-α, contribute to the pathology and progression of numerous diseases, such as inflammatory diseases and cancers." (PMID 36611025, 2023). "IL-6 is important inflammatory factor that can activate the STAT3 signaling pathway to induce chemoresistance and radioresistance in a variety of cancer cells." (PMID 36635302, 2023). "In 54 SSc patients, there were significantly increased serum levels of IL-6, TNF-α, monocyte chemoattractant protein 1 (MCP1) (cancer-promoting), but also reduced IFN-γ and macrophage derived chemokine (MDC) (cancer-suppressive)." (PMID 37681925, 2023). "ORM1 is an acute-phase protein whose levels increase rapidly under conditions of inflammation, stress, chronic diseases (cancer, etc.)and injury and can be modulated by glucocorticoids, TNF-α, IL-1, IL-8, IL-6, and IL-6-related cytokines." (PMID 37355563, 2023). "The cancer group had higher TNFAIP8 serum (Wilcoxon, p < 0.001) and IL-6 levels (Wilcoxon, p < 0.001) when compared with the control group." (PMID 37296861, 2023). "CAFs produce many substances such as IL-6, IL-8, and TGF-β impacting cancer progression and immunosuppression." (PMID 37480115, 2023). "Pro-inflammatory mediators, such as TNF-α, IL-6, IL-1B, and MCP-1, are involved in the secondary activation of many genes involved in the pathogenesis of inflammation and cancer." (PMID 37103287, 2023). "We recently reported that Compound B potently inhibited the HMGB1-stimulated IL-6 production in mouse macrophage-like cells RAW264.7, suggesting dual suppressive actions: anti-inflammatory and anti-cancer activities." (PMID 37505064, 2023).
cancer (continued). "There is evidence suggesting that urinary IL-2 levels as well as IL-6, IL-8, IL-12, TNF-α, and IFN-γ are promising markers in predicting BCG clinical responses suggesting cytokines as a potential treatment for cancer." (PMID 37588093, 2023). "Using IL6- and Myd88- knockout mice, it was shown that LCN-2 is an inflammation-induced factor in cancer cachexia." (PMID 37006254, 2023). "Taken together, IL-6 acts as a key mediator of the EMT switching and metastatic acquisition in the NK-LAAO-treated cancer cells." (PMID 37385076, 2023). "These include TNF-α, interleukins (IL-6; IL-1β and IL-1α), interferon-gamma (IFN-γ), leukemia inhibitory factor (LIF), and the TGF-β superfamily have been shown to mediate cancer-induced muscle wasting." (PMID 38203683, 2023). "Our data demonstrated the synergistic inducing EMT effect of IL-6 combined with hypoxia via the IL-6/STAT3/HIF-1α autocrine loop, which contributes to understanding cancer progression and invasiveness, and developing a feasible therapeutic strategies for EOC." (PMID 36814597, 2023). "Hence, a more in-depth investigation into the function of cytokine-induced inflammation and cancer-associated muscle atrophy, with a particular focus on the participation of TNF-α, IL-1, IL-6, and IFNγ, could yield significant knowledge regarding the fundamental mechanisms involved." (PMID 37959329, 2023). "IL-6 levels in the TME and in the sera of cancer patients have been correlated with poor disease outcomes." (PMID 36949244, 2023). "Elevated levels of IL-1β, IL-6, and TNF-α impair systemic insulin sensitivity and promote cancer development." (PMID 37175211, 2023). "Epithelial cells in numerous cancer types have been shown to undergo EMT and acquire an invasive morphological phenotype following exposure to IL-6; however, the potential pathways of induction of EMT in EOC are not well understood." (PMID 36814597, 2023). "It has also been found that cancer cells are capable of directly synthesizing these factors, resulting in in vitro expression of TNF-α and IL-6 1000-fold higher in cancer cells compared to physiological ovarian epithelial cells." (PMID 37190027, 2023). "Aromatase is induced in adipocytes by pro-inflammatory factors (such as IL6, TNFα) and adipokines (such as leptin), secreted by the adipocytes themselves, or by other cytotypes in the TME, including inflammatory cells and cancer cells themselves." (PMID 37561190, 2023). "MDSCs also confer cancer cells with stem-like characteristics and EMT through IL6- and NO-mediated STAT3 and NOTCH pathway activation." (PMID 36632469, 2023). "Collectively, these factors, including the excessive expression of IL-17, IL-6, TNF-α, altered gene expression, and vascular leakage, contribute to a cancer-favorable environment." (PMID 37892997, 2023). "The results of this study show that The active components of the A. cantoniensis Hance can affect cancer signaling pathway, endocrine resistance, PI3K-AKt signaling pathway, MAPK signaling pathway, IL-2/IL-6/IL-17 signaling pathway and TNF signaling pathway." (PMID 37035802, 2023). "Interleukin 6 (IL-6) acts on cancer cells by inducing the expression of STAT3-dependent genes, thereby promoting cancer cell proliferation and survival." (PMID 37460938, 2023). "In certain cancers that progress toward cachexia, the release of various cytokines, such as TNF-α, IL-6, and interferon gamma (IFN-γ), plays a significant role." (PMID 37755304, 2023). "From the Elisa results, BMDCs in LT and LRT groups secreted higher amounts of IL-6, TNF-α, IL12p70, and IL-1β than in other groups, indicating the successful DCs maturation by upregulating CRT expression on cancer cell’s surface." (PMID 37951973, 2023). "The infiltration of immune cells related to almost all cancers is a source of secretion of inflammatory cytokines including IL-6 and tumour necrosis factor–alpha (TNF-alpha), which is an important link to cancer–inflammation interactions." (PMID 37753372, 2023).